KEAP1 (kelch like ECH associated protein 1)
Diseases named in the same sentence as KEAP1 in open-access papers (continued):
Sharing a sentence is not in itself a finding about the gene and the disease.
Alport syndrome (1 paper, 2025). A rare renal disease characterized by glomerular nephropathy with hematuria progressing to end-stage renal disease (ESRD), frequently associated with sensorineural deafness, and occasionally with ocular anomalies. "Our study provides a comprehensive insight into the efficacy of Nrf2 activation in Alport syndrome and provides a rationale for adding a Keap1-Nrf2 interaction inhibitor to a renin–angiotensin system inhibitor." (PMID 40527586, 2025). "Together, our study provides a comprehensive insight into the direct relationship among Nrf2 activation, proteinuria, and kidney disease progression in Alport syndrome, and indicates better efficacy of adding a Keap1-Nrf2 PPI inhibitor to ARB." (PMID 40527586, 2025). "Overall, these results provide a comprehensive insight into the ameliorative effect of Nrf2 in Alport syndrome and may indicate better efficacy of adding a Keap1-Nrf2 PPI inhibitor to the RAS inhibitor." (PMID 40527586, 2025). "We recently demonstrated that the Keap1-Nrf2 protein–protein interaction (PPI) inhibitor UBE-1099 transiently increased proteinuria, but attenuated kidney disease progression in the Alport syndrome mouse model (B6.Cg-Col4a5tm1Yseg/J)." (PMID 40527586, 2025).
anaplastic astrocytoma (1 paper, 2024).
autism (1 paper, 2025). Persistent deficits in social interaction and communication and interaction as well as a markedly restricted repertoire of activity and interest as well as repetitive patterns of behavior. "The aim of this study was to measure the levels of Nrf2, Keap1 protein, glutathione, and key enzymes involved in its metabolism in the blood of young patients in both autism and neurotypical groups." (PMID 40227289, 2025). "In contrast, one study found elevated serum levels of Keap1 and Nrf2 in children with autism along with reduced levels of heme oxygenase-1 (HO-1), a key antioxidant enzyme whose gene expression is regulated by Nrf2." (PMID 40227289, 2025). "Children with autism had significantly lower plasma levels of GSH, GR, Nrf2, and Keap1 (p < 0.05), as well as a lower R-index value (p < 0.001), compared to the healthy children." (PMID 40227289, 2025).
autism spectrum disorder (1 paper, 2025). A spectrum of developmental disorders that includes autism, and Asperger syndrome. "Our study reveals altered antioxidant defense in children with autism spectrum disorder, as evidenced by reduced levels of Nrf2, Keap1, GSH, and GR, along with elevated GSSG and a lower GSH/GSSG ratio." (PMID 40227289, 2025). "Evidence suggests that Nrf2 levels and Nrf2/Keap1 activity may also be disrupted in autism spectrum disorders." (PMID 40227289, 2025).
autoimmune hepatitis (1 paper, 2024). Hepatitis caused by autoantibodies. "A study using concanavalin A (Con A)-induced autoimmune hepatitis (AIH) model in mice verified the pharma-cological activity of KM in steatohepatopathy, KM activated the Nrf2 pathway, upregulated the expression of antioxidant factors HO-1 and Nrf2 and downregulated the expression of Keap1." (PMID 38686320, 2024).
Autoimmunity (1 paper, 2020). The occurrence of an immune reaction against the organism's own cells or tissues. "The Keap1/Nrf2 system is known to play important roles in redox balance and metabolic homeostasis, with documented beneficial effects in models of inflammation, autoimmunity, metabolic, and neurodegenerative diseases, and many other chronic conditions." (PMID 33158045, 2020).
autosomal dominant polycystic kidney disease (1 paper, 2021). Autosomal dominant form of polycystic kidney disease. "It has been demonstrated that activation of Nrf2 or inhibition of Keap1 protects against kidney diseases such as acute kidney disease, autosomal dominant polycystic kidney disease, and CKD." (PMID 34426758, 2021).
bacterial pneumonia (1 paper, 2024). Acute infection of the lung parenchyma caused by bacteria (e.g., Streptococcus pneumoniae, Haemophilus influenzae, Chlamydia pneumoniae, Mycoplasma pneumoniae, and Legionella pneumophila). "Rosmarinic acid can bind to Keap1, blocking the association between Keap1 and Nrf2 and activating Nrf2, thereby relieving bacterial pneumonia." (PMID 38975345, 2024).
bile duct cancer (1 paper, 2016). "It has been reported that up-regulation of Keap1 gene expression inhibits Nrf2 nuclear translocation in human bile duct cancer cells." (PMID 27280406, 2016).
bone cancer (1 paper, 2026). A primary or metastatic malignant neoplasm affecting the bone or articular cartilage. "In the bone cancer pain model, ZC3H15 exacerbates neuronal oxidative stress through the KEAP1/NRF2 pathway and activates microglial inflammatory response through IκB α/NF - κ B activation." (PMID 41513632, 2026).
bone metastasis (1 paper, 2022). Transfer of a neoplasm from its primary site to bones. "In the atezolizumab arm, several characteristics were associated with early versus late progression (P < 0.1), including liver or bone metastasis, higher baseline SLD, squamous histology and presence of KEAP1 mutations." (PMID 35995953, 2022).
brain cancer (1 paper, 2024). A primary or metastatic malignant neoplasm affecting the brain. "Chemoprevention in brain cancer by activation of Nrf2/Keap1/ARE pathway has come up as a very attractive approach, and therapeutic exploitation on this approach can lead to groundbreaking discoveries in the treatment and prevention of brain tumors." (PMID 39407193, 2024). "Clearly, the findings suggest that extensive studies are required to determine the specific and dose-dependent activities and mechanisms of modulation of Nrf2/Keap1/ARE pathway to optimize its therapeutic attribute against brain cancer." (PMID 39407193, 2024). "Emerging evidence suggests that inhibition of the Nrf2/Keap1/ARE pathway provides chemotherapeutic effects against cancers including brain cancer." (PMID 39407193, 2024). "Multiple advances in the understanding of Nrf2 signaling in brain cancer have emerged, but still a great deal of investigations remains to be performed to determine the specific mechanistic and functional underpinnings of the dual role of Nrf2/Keap1/ARE cascade." (PMID 39407193, 2024).
brain tumors (1 paper, 2024). "Modulation of Nrf2/ARE and downstream activities in a Keap1-dependant manner, with the aid of plant-derived secondary metabolites exhibits promise in the management of brain tumors." (PMID 39407193, 2024). "Current article highlights the effects of Nrf2/Keap1/ARE cascade on brain tumors, and the potential role of secondary metabolites regarding the management of the same." (PMID 39407193, 2024). "Emerging evidence reveals that modulating Nrf2/ARE and downstream antioxidant enzymes in a Keap1-dependant manner, with the aid of multiple plant-derived secondary metabolites might play pivot in the management of brain tumors." (PMID 39407193, 2024). "Emerging evidence reveals that regulating Nrf2/ARE and downstream antioxidant enzymes by the use of Keap1 modulators, might play pivot in the management of brain tumors." (PMID 39407193, 2024).
chronic heart failure (1 paper, 2025). "Conversely, upregulation of Nrf2 following deletion of Keap1 in the same area reduced sympathetic nerve activity in mice with chronic heart failure." (PMID 41462690, 2025).
chronic tubulointerstitial nephropathy (1 paper, 2019). "The increased cytosolic Keap1 in both CL and UUO kidneys seems at first sight be contradictory with a similar increment in nuclear Nrf2: in a model of CKD, Western blotting analysis indicated an inverse relationship between Nrf2 and Keap1 in chronic tubulointerstitial nephropathy." (PMID 31251767, 2019).
colon diseases (1 paper, 2019). "Keap1/Nrf2 signaling pathway, an important endogenous antioxidative stress pathway, plays an essential role in colon diseases." (PMID 32116661, 2019).
colorectal adenoma (1 paper, 2021). An adenoma that arises from the colon or rectum. "The authors found that Keap1 knockdown and Nrf2 activation impacted the metabolism of the non-tumoral colon, but did not affect colorectal adenoma formation in this model." (PMID 34526660, 2021). "Indeed, neither genetic (by Keap1 knockdown) nor pharmacological Nrf2 activation, nor its disruption, affected colorectal adenoma formation in this model." (PMID 34526660, 2021).
corneal diseases (1 paper, 2017). "In summary, the Nrf2/Keap1/ARE signaling pathway is a promising therapeutic target against oxidative stress for corneal diseases." (PMID 29209447, 2017).
diabetes insipidus (1 paper, 2017). A disorder characterized by excretion of large amounts of urine, accompanied by excessive thirst. "Renal tubular deletion of Keap1 promotes nephrogenic diabetes insipidus features, confirming that Nrf2 activation in developing tubular cells causes a water reabsorption defect." (PMID 28233855, 2017).
disc degeneration (1 paper, 2021). "In summary, we have demonstrated that TP, a plant-derived natural antioxidant agent, plays an important role in activating the Keap1/Nrf2/ARE pathway and delaying disc degeneration." (PMID 33505586, 2021).
esophageal disease (1 paper, 2012). "In addition to a mechanistic understanding of human esophageal disease, manipulation of the Nrf2/Keap1 pathway may provide a novel way of enhancing the protective barrier of the esophageal epithelium." (PMID 22567161, 2012).
frontotemporal dementia (1 paper, 2021). Frontotemporal dementia (FTD) comprises a group of neurodegenerative disorders, characterized by progressive changes in behavior, executive dysfunction and language impairment, as a result of degeneration of the medial prefrontal and frontoinsular cortices. "Mutations of SQSTM1 have been associated with the risk for frontotemporal dementia (FTD), with mutations leading to disrupted interactions between KEAP1 and SQSTM1." (PMID 35052512, 2021).
gastric diseases (1 paper, 2024). "These current findings showed that AOS can trigger the p62/Keap1/Nrf2 axis in gastric epithelial cell lines, representing a potential new therapeutic target to combat oxidative stress in gastric diseases." (PMID 38790723, 2024).
glomerulopathy (1 paper, 2019). "Similarly, in a murine model of glomerulopathy, genetic knockdown of Keap1 promoted the constitutive Nrf2 activity but failed to diminish proteinuria." (PMID 31349118, 2019).
Gordon syndrome (1 paper, 2014). An extremely rare multiple congenital malformation syndrome characterized by congenital contractures of hand and feet with variable degrees of severity of camptodactyly, clubfoot and, less frequently, cleft palate. "Parallel to Gordon's syndrome mutations in KLHL3, several of the reported KEAP1 mutations directly perturb the interface with NRF2, whereas others are likely to disrupt the structural integrity of the Kelch domain fold." (PMID 24641320, 2014).
HCMV infection (1 paper, 2023). "There are limited studies on the modulation of the Keap1-Nrf2 pathway during HCMV infection and its role in restricting HCMV replication." (PMID 36939350, 2023).
Hemoglobinopathies (1 paper, 2023). "In this review, we will discuss the role of the Keap-1–Nrf2 complex in hemoglobinopathies, especially in SCD, and how this complex might represent a better target for more effective treatment options." (PMID 36978988, 2023). "Nrf2 through Keap1 directly induces the expression of gamma globin that can compensate for the globin imbalance, making thus Nrf2 the most plausible target to treat the β-globin hemoglobinopathies." (PMID 36978988, 2023).
hemorrhagic stroke (1 paper, 2018). A stroke caused by a bleed on the brain. "Of the hemorrhagic stroke, pathway involving Keap1 (Kelch-like ECH-associated protein 1) and Nrf2(nuclear factor erythroid 2-related factor 2), a major endogenous antioxidant system is considered as a key therapeutic which can limiting the over production of ROS by mitochondria after ICH." (PMID 30501621, 2018).
hepatitis C virus infection (1 paper, 2019). A viral infection caused by the hepatitis C virus. "For example, KPNA6 mediates Kelch-like ECH-associated protein 1 (Keap1)/Nuclear factor erythroid 2–related factor 2 (Nrf2) signaling pathway, affecting IFNα antiviral response, oxidative stress, and autophagy during hepatitis C virus infection." (PMID 31717720, 2019).
hereditary leiomyomatosis and renal cell cancer (1 paper, 2020). Hereditary leiomyomatosis and renal cell cancer (HLRCC) is a hereditary cancer syndrome characterized by a predisposition to cutaneous and uterine leiomyomas and, in some families, to renal cell cancer. "For example, in hereditary leiomyomatosis and renal cell cancer (HLRCC), a high level of fumarate caused by genetic mutation of fumarate hydratase induces the succination of Kelch-like ECH-associated protein 1 (KEAP1) accompanied by the consumption of a fumarate molecule." (PMID 32943735, 2020).
Huntington disease (1 paper, 2019). Huntington disease (HD) is a rare neurodegenerative disorder of the central nervous system characterized by unwanted choreatic movements, behavioral and psychiatric disturbances and dementia. "Up to now, only a few disease models related to the Keap1–Nrf2 PPI have been evaluated in lab and clinical research, such as mouse renal inflammation, Huntington’s disease, drug-induced liver injury, and many cancer models." (PMID 31509940, 2019).
hypertrophic cardiomyopathy (1 paper, 2021). A condition in which the myocardium is hypertrophied without an obvious cause. "Several researches have shown sustained activation of the Nrf2/Keap1 redox sensing pathway, which ultimately led to age-dependent cardiac dysfunction and hypertrophic cardiomyopathy." (PMID 34840667, 2021).
hypopharyngeal carcinoma (1 paper, 2025). Carcinoma, predominantly squamous cell, arising from the epithelial cells of the hypopharynx. "Although the study did not employ hypopharyngeal carcinoma cell lines, it highlighted significant mutations in NRF2 and KEAP1 in hypopharyngeal carcinoma cells, suggesting a high likelihood that these cells similarly acquire chemoresistance via the NRF2 axis." (PMID 41153768, 2025).
insomnia (1 paper, 2025). A sleep disorder characterized by difficulty in falling asleep and/or remaining asleep. "In conclusion, GAD67 negatively regulates insomnia, and senegenin can regulate insomnia by mediating the expression of cytokines in the GAD67‐regulated Keap1/Nrf2/Parkin/PINK1 pathway." (PMID 39380353, 2025). "Therefore, in this study, GAD67 lentivirus was transfected at the epigenetic level in vitro and in vivo to explore the mechanism of senegenin in regulating insomnia through the GAD67‐mediated Keap1/Nrf2/Parkin/PINK1 pathway." (PMID 39380353, 2025). "Therefore, considering better safety, we chose GAD67 expression in viral vectors to explore how senegenin mediates the Keap1/Nrf2/Parkin/PINK1 pathway to regulate insomnia through GAD67." (PMID 39380353, 2025). "We measured GAD67 expression levels in insomnia patients and evaluated the expression levels of GAD67 and Keap1/Nrf2/Parkin/PINK1‐related cytokines following GAD67 lentiviral transfection in PC12 cells and in rat models." (PMID 39380353, 2025). "In this study, we showed that Keap1 expression was increased and Nrf2, NQO1, and HO‐1 expression was decreased in insomnia rats, and after senegenin intervention, Keap1 expression was decreased and Nrf2, NQO1, and HO‐1 expression was increased." (PMID 39380353, 2025). "GAD67 is negatively correlated with sleep–wake rhythm and can regulate Keap1/Nrf2/Parkin/PINK1 expression, and senegenin can further regulate Keap1/Nrf2/Parkin/PINK1 by mediating GAD67, thus playing a regulatory role in the development of insomnia." (PMID 39380353, 2025).
invasive ductal breast carcinoma (1 paper, 2011). The most common type of invasive breast carcinoma, accounting for approximately 70% of breast carcinomas. "We assessed immunohistochemical expression of 8-OHdG, Nrf2, Keap1, PRDX III and PRDX IV in 79 women with invasive ductal breast carcinomas." (PMID 21693047, 2011).
laminopathy (1 paper, 2025). A rare genetic disorder caused by mutations in genes encoding proteins of the nuclear lamina. "We have already discussed the role of the Keap1-dNrf2 (CncN) pathway in response to xenobiotic stress and oxidoreductive stress in the context of Drosophila lamin C laminopathy mutations above." (PMID 40940714, 2025). "Based on the results, the authors proposed a new model of muscle laminopathy development in Drosophila adult muscles, which is independent of the Keap1–Nrf2 reductive/oxidative stress pathway." (PMID 40940714, 2025).
large cell neuroendocrine carcinoma (1 paper, 2022). A usually aggressive carcinoma composed of large malignant cells which display neuroendocrine characteristics.
lipodystrophy (1 paper, 2023). A congenital or acquired disorder characterized by abnormal loss or redistribution of the adipose tissue in the body. "Indeed, blood glucose levels were decreased in Kp1A/A::RosaNIC/NIC::AdiCre mice but not in Kp1B/B background mice, suggesting systemic metabolic effects driven by Keap1 hypomorphic expression are one of the key elements in inter-organ communication that is disturbed in the setting of lipodystrophy." (PMID 37686150, 2023).
lung tumors (1 paper, 2013). "Certain heterozygous mutations in KEAP1, previously identified in human lung tumors, were also found to have a dominant negative effect on wild-type KEAP1, using an in vivo system in transgenic mice." (PMID 23577226, 2013). "Genetic studies of human lung tumors (AC, SCC) further substantiate this, and some suggest that tumor types may have distinct patterns of KEAP1 mutation frequency." (PMID 23577226, 2013).
male reproductive system diseases (1 paper, 2023). "Thus, the JAK2/STAT3 and Keap1/Nrf2 pathways and their components can be considered therapeutic targets for drug design to manage male reproductive system diseases." (PMID 37759514, 2023).
metastatic carcinoma (1 paper, 2025). A carcinoma which has spread from the original site of growth to another anatomic site. "A biopsy from the right supraclavicular lymph node was also obtained showing metastatic carcinoma with high tumor mutation burden 13.3 mutations/MB, microsatellite instability negative, KRAS p.(Gly12Cys), KEAP1 p.(Glu446TER), KEAP1 p.(Gly477Val), and NTRK1 p.(Asp509His)." (PMID 41476748, 2025).